ANOS2P (anosmin 2, pseudogene)
Synonyms: KAL-Y; formerly ADMLY; KALP
Gene: Transcribed unprocessed pseudogene on chromosome Y (13,751,656 to 13,915,824, forward strand). Ensembl gene ENSG00000241859.
Diseases named in the same sentence as ANOS2P in open-access papers:
ANOS2P is named in the same sentence as 1 disease in open-access papers, as found by Europe PMC text mining. Sharing a sentence is not in itself a finding about the gene and the disease.
ANOS2P shares sentences with these, for which no sentence is quoted: Kallmann syndrome (2 papers).